CD46 (CD46 molecule)
Diseases named in the same sentence as CD46 in open-access papers (continued):
Sharing a sentence is not in itself a finding about the gene and the disease.
cancer (continued). "Some signaling communication networks (CD46, HSPG, EGF, CEACAM, PDGF, and EDN) exclusively involved high PAK2-expressing cancer cells, with no participation from low PAK2-expressing cancer cells." (PMID 38343537, 2024). "Interestingly, the expression of CD46, CD55, and CD59 was suppressed in U2-OS cells compared with human endothelial cells or other cancer cells which did not activate the complement system." (PMID 29615744, 2018).
adenocarcinoma (6 papers, 2011 to 2023). A common cancer characterized by the presence of malignant glandular cells. "Nearly homogeneous CD46 mRNA expression was found in 10/10 small cell neuroendocrine and about 36/36 adenocarcinoma mCRPC patient samples." (PMID 36906664, 2023). "We discovered a new lineage independent cell surface antigen CD46 that is homogeneously expressed in both adenocarcinoma and small cell neuroendocrine subtypes." (PMID 36906664, 2023). "We have shown previously that CD46 is expressed in both adenocarcinoma and small cell neuroendocrine prostate cancer." (PMID 36906664, 2023). "The use of SLAM/CD46 blind MV that retained the ability to bind PVRL4 could constitute a potential therapeutic vaccine against adenocarcinoma." (PMID 21901103, 2011). "Based on the human adenocarcinoma alveolar epithelial cell line A549, three stable knockout cell lines were established carrying knockouts for CAR, CD46 or a double knockout for CAR and CD46." (PMID 35269463, 2022). "Toxicology studies of biotinylated anti-CD46 mixed with Streptavidin-ZAP were performed in non-human primates that showed the potential of CD46 for use as a target in adenocarcinoma and neuroendocrine types of metastatic castration-resistant prostate cancer (mCRPC)." (PMID 36977072, 2023).
bacterial infections (3 papers, 2016 to 2024). "In conclusion, we demonstrated for the first time that a teleost CD46 inhibited complement activation through recruitment of factor I, and was able to facilitate bacterial infection by serving as a cellular receptor for bacterial pathogens." (PMID 29101395, 2017). "The present study, with an aim to gain more insights into the function of teleost CD46, we examined the biological role in complement activation and during bacterial infection in tongue sole (Cynoglossus semilaevis)." (PMID 29101395, 2017).
kidney (2 papers, 2018 to 2022). "Since CD46 also acts as a cofactor of FI-mediated cleavage of C3b, certain CD46 polymorphism was found to be associated with reduced acute rejection and better allograft survival in kidney transplant recipients." (PMID 35281019, 2022).
blood cancers (1 paper, 2023). "Expanding the protein-protein interaction analysis for blood cancers revealed an additional network consisting of CD46, CFP, MASP1 and SERPINE1, correlated with short overall survival." (PMID 36649303, 2023).
brain disorder (1 paper, 2021). A disease affecting the brain or part of the brain. "CD46 transgenic mice developed progressive infectious measles encephalitis similar to brain disorders in immunocompromised patients." (PMID 34408631, 2021).
infectious disease (1 paper, 2021). A disorder directly resulting from the presence and activity of a microbial, viral, or parasitic agent in humans. "CD46 plays a key role in several infectious diseases and has been designated as a “pathogen magnet”." (PMID 34831317, 2021). "Individuals with CD46 or Jagged1 mutations do not develop Th1 responses and are extremely susceptible to infectious diseases during childhood." (PMID 34831317, 2021).
CD46 also shares sentences with these, for which no sentence is quoted: multiple myeloma (9 papers); hemolytic-uremic syndrome (5); Alzheimer disease (3); C3 glomerulopathy (3); dementia (3); glioblastoma (3); immune disorders (3); kidney disease (3); immunodeficiencies (2); systemic sclerosis (2); thalassemia (2); urinary tract infection (2); acute kidney injury (1); acute myelogenous leukemia (1); acute respiratory distress syndrome (1); adenosquamous carcinoma (1); Alagille syndrome (1); antibody deficiency (1); Arthritis (1); brain tumor (1); butyrylcholinesterase deficiency (1); Chagas disease (1); chronic periodontitis (1); Cirrhosis (1); co-infection (1); cognitive decline (1); colorectal adenocarcinoma (1); Coronary Artery Disease (1); cutaneous T-cell lymphomas (1); diabetic retinopathy (1).
A further 43 diseases each share a sentence with CD46 in 1 paper.